AFP (alpha fetoprotein)
Diseases named in the same sentence as AFP in open-access papers (continued):
Sharing a sentence is not in itself a finding about the gene and the disease.
tumor (continued). "Selection should be guided by integrated assessment of response durability, tumor biology, AFP trends, and patient comorbidities." (PMID 41186530, 2026). "Key markers included C-reactive protein, albumin, neutrophil and lymphocyte counts, creatinine, bilirubin, international normalized ratio, tumor size and number, alpha-fetoprotein, platelet count, and CD4+/CD8+ T-cell levels." (PMID 41869666, 2026). "We got the RANBP3L is corrected with LIHC clinical characteristics such as pathologic M stage, tumor status, AFP (ng/ml), and histologic grade." (PMID 41457788, 2026). "Serum tumor markers, including alpha-fetoprotein, beta-human chorionic gonadotropin, and lactate dehydrogenase, remained within normal limits." (PMID 42254200, 2026). "CBD reduced serum levels of ALT, AST, GGT, and AFP, improved hepatic architecture, and decreased tumor aggressiveness in DENA-treated rats." (PMID 41562849, 2026). "SREBP2 levels were quantified via ELISA (sensitivity: 0.1 ng/mL) and then incorporated into a multivariate Cox model alongside tumor number and AFP to predict recurrence-free survival (RFS)." (PMID 42008358, 2026). "To further evaluate the clinical utility of ATX, we systematically compared it with both tumor markers (AFP, PIVKA‐2) and fibrosis markers (HA, 4C7S, FIB‐4, M2BPGi) for post‐RFA recurrence prediction." (PMID 41499228, 2026). "AFP elevation was rare in GEP-NENs but consistently associated with advanced disease, high tumor grade, and increased proliferative activity." (PMID 41938105, 2026). "Serum tumour markers showed elevated β-human chorionic gonadotropin and lactate dehydrogenase, with normal alpha-fetoprotein." (PMID 42078164, 2026). "Laboratory tests showed normal levels of tumor markers including alpha-fetoprotein (AFP), carcinoembryonic antigen (CEA), carbohydrate antigen 19-9 (CA19-9), and carbohydrate antigen 125 (CA125)." (PMID 42040540, 2026). "Tumor-derived alpha-fetoprotein binds more PUFAs than does umbilical blood-derived alpha-fetoprotein, which induces a glycolytic phenotype in dendritic cells." (PMID 41526343, 2026). "PSM was performed (90Y:DEB-TACE), matching for tumor burden and alpha-fetoprotein levels at diagnosis." (PMID 42008775, 2026). "Clusters 3 and 4 exhibit profiles similar to Clusters 1 and 2, but differ in having larger tumor size and higher AFP values." (PMID 41536859, 2026). "The RANBP3L expression was significantly related to pathologic M stage, tumor status, AFP (ng/mL), and histologic grade in LIHC." (PMID 41457788, 2026). "CONCLUSION: AFP-producing HCC is linked to intra-tumoral immune exhaustion, marked by PD-1high CD8+ T cell accumulation, suggesting a localized immunosuppressive effect mediated by tumor-secreted AFP." (PMID 41632329, 2026). "For 18F-FDG and 18F-FEC, standardized uptake values (SUV maximum, mean, and peak) and metabolic tumor volume were measured, along with lesion size, MRI enhancement ratios, AFP levels, and survival." (PMID 42192887, 2026). "Factors considered tend to include tumor size and number, lobar distribution, multinodularity, α-fetoprotein (AFP) level, degree of tumor differentiation, vascular invasion, and satellite nodules." (PMID 41828017, 2026). "The complementary role of imaging (e.g., fat‐fluid levels on CECT) and tumor markers (normal AFP, catecholamines) is essential for narrowing the differential." (PMID 41476812, 2026). "Combined clinico-radiological models-incorporating albumin-bilirubin (ALBI) grade, BCLC stage, alpha-fetoprotein (AFP) level, tumor diameter, distribution, and peritumoral arterial-phase enhancement-consistently outperformed single-source models." (PMID 42294337, 2026). "Tumour serum markers (e.g. alpha‐fetoprotein, beta‐subunit of human gonadotropin and microRNAs) are helpful in the diagnosis and for follow‐up analysis to detect recurrent disease or disease progression." (PMID 41384700, 2026).
tumor (continued). "The Authors found that among combinations of three parallel detections of BC tumour markers, AFP+CEA+CA15-3 had the highest sensitivity (SN 83.46%) and CEA+CA125+CA19-9 had the highest AUC (AUC = 0.922)." (PMID 40844552, 2025). "In multivariate Cox regression analyses, AFP, ECOG performance status, Child-Pugh score, and intrahepatic tumor size, PBIShi, NLR, and CRP were associated with OS." (PMID 40568585, 2025). "Significant predictors of OS included preoperative AFP levels (P = 0.048), Child-Pugh classification (P = 0.029), time to recurrence (P = 0.001), microvascular invasion (P = 0.011), and tumor differentiation (P = 0.013)." (PMID 39816698, 2025). "At the same time, other tumor markers such as AFP and CYFRA21-1 were occasionally abnormal in individual patients." (PMID 41210047, 2025). "The diagnosis of HCC is based on imaging (US/CESU/CT/MRI) and serum tumor makers such as alpha-fetoprotein (AFP) and des-γ-carboxy prothrombin (DCP)." (PMID 39860320, 2025). "Univariate analysis identified serum AFP levels, tumor number, tumor size, macrovascular invasion, microvascular invasion (MVI), BCLC stage, TNM-T stage, preoperative CTC, and VETC as significant factors for OS and DFS." (PMID 40657396, 2025). "As for tumor markers, serum carcinoembryonic antigen, alpha fetoprotein, ca153, SCC levels were all normal in the tested 10 cases." (PMID 39833069, 2025). "Our case highlights the efficacy and safety of icaritin in treating advanced HCC with pulmonary metastasis, characterized by reduced AFP levels, diminished tumor size, and minimal side effects." (PMID 40035422, 2025). "Second, HP incorporates molecular variables from tumoral tissue, offering a more direct assessment of tumor biology than biomarkers like AFP and DCP, which have limited sensitivity and specificity." (PMID 39941867, 2025). "All of these results point to the effectiveness of canagliflozin treatment for anti-hepatocarcinogenesis, as it decreased the levels of tumor markers: AFP, AFU, and CEA." (PMID 40439888, 2025). "All the serum tumor marker levels, including alpha-fetoprotein (AFP), protein induced by vitamin K absence or antagonist-II (PIVKA-II), carcinoembryonic antigen (CEA), and carbohydrate antigen 19-9 (CA19-9), were within normal limits." (PMID 40276287, 2025). "Following completion of five chemotherapy cycles, the tumor marker levels showed marked reduction: AFP 78 ng/mL, CEA 189 ng/mL, CA15.3–46 U/mL, CA125–20 U/mL, and CA19.9–59 U/mL." (PMID 41409243, 2025). "Tumor markers demonstrated alpha-fetoprotein (AFP) of 3.4 ng/mL, carcinoembryonic antigen (CEA) of 1.2 ng/mL, carbohydrate antigen 19-9 (CA 19-9) of 639 U/mL, cancer antigen 15-3 (CA 15-3) of 17 U/mL, and CA 125 of 55 U/mL." (PMID 40918798, 2025). "In the CHCC dataset, oncoScore was correlated with higher serum AFP levels, presence of tumour thrombus and advanced BCLC stage." (PMID 41383134, 2025). "Tumor markers (beta-human chorionic gonadotropin (β-hCG), alpha-fetoprotein (AFP), and lactate dehydrogenase (LDH)) were within normal limits." (PMID 40978995, 2025). "↓ tumour progression markers: AFP, AFU and CEA, levels;↓ oxidative stress marker: MDA levels;↑ antioxidant markers: SOD and GSH levels." (PMID 41471707, 2025). "In the testing cohort, significant differences were found in PCOS, maximum tumor diameter, AFP, ALB, and HE4 levels." (PMID 41264387, 2025). "HBCV-HCC patients exhibited lower tumor grade (grade 3–4: 29% vs. 42%, P = 0.0345*) and lower AFP level (≥ 100 ng/mL: 27% vs. 43%, P = 0.0061**) than mono-infected HCC patients." (PMID 39743539, 2025). "This study tried to understand the status of HCC after EBRT and determine the value of tumor markers through careful observation of AFP and PIVKA-II." (PMID 40392828, 2025). "Postoperative pathology revealed high-grade muscle invasive bladder urothelial carcinoma and immunohistochemical staining of the tumor cells showed strong AFP positivity." (PMID 40406259, 2025).
tumor (continued). "Elevated AFP not only indicates a poor outcome but also actively promotes tumor progression by enhancing proliferation, invasion, and migration." (PMID 40655149, 2025). "Research has shown that after receiving IORT-DT, the average level of tumour marker AFP in EG patients decreased by 16.2 ng/mL, nearly twice as high as the 8.6 ng/mL in CG (P<0.05)." (PMID 40951893, 2025). "Individual tumor markers, including AFP and PIVKA-II, showed moderate predictive accuracy, with slightly better performance in the Beyond Milan cohort." (PMID 40656560, 2025). "The current risk stratification largely relies on the histopathological staging and serum tumor markers, such as alpha-fetoprotein (AFP), beta-human chorionic gonadotropin (beta-hCG), and lactate dehydrogenase (LDH)." (PMID 40528068, 2025). "We also analyzed the liver tissue of HCC patients and found that the expression of RBM17 was positively correlated with tumor size and AFP value, indicating its potential role in HCC progression and poor prognosis." (PMID 40702000, 2025). "These restrictions reduced the variability and statistical power of AFP and tumor size in the multivariate model." (PMID 40937437, 2025). "This regimen achieved a temporary response: serum AFP levels decreased and the primary tumor shrank." (PMID 40922714, 2025). "The AFP reduction seen in the RT group supports a potential mechanistic link between lenvatinib-induced radiosensitization and enhanced intrahepatic tumor control." (PMID 41029243, 2025). "At the time of diagnosis, serum tumor markers were elevated, with an AFP level of 1,163.73 ng/mL and LDH at 3170 U/L." (PMID 41230344, 2025). "Emerging evidence highlights the importance of personalized approaches, such as integrating tumor biology and biomarkers like AFP and DCP into scoring systems, to improve prognostic accuracy." (PMID 40427147, 2025). "In multivariate analysis, the maximal tumor size, alpha fetoprotein level, and treatment modality emerged as significant prognostic factors for OS (P all < 0.05)." (PMID 40406260, 2025). "Suspecting malignancy, a side view endoscopy was planned, and tumor markers (AFP, CA 19-9 and CEA) were ordered, which showed an ulcerated ampullary mass of ~1.5 cm in size causing common bile duct obstruction and a normal stomach and esophagus." (PMID 40162142, 2025). "At the end of 4 cycles, the tumor had shrunk to 43 × 29 × 36 mm, and the AFP level had decreased to within the normal range." (PMID 41000245, 2025). "In this study, CD90(+) CTCs demonstrated superior dynamic monitoring compared to conventional tumor markers such as AFP and DCP." (PMID 40940925, 2025). "The 2022 update of the BCLC classification system emphasized the importance of patients’ serum AFP levels, liver function, and tumor burden in determining the treatment administered to patients with HCC." (PMID 40075741, 2025). "Several tumor markers, such as alpha-fetoprotein (AFP), carcinoembryonic antigen (CEA), cancer antigen (CA) 19-9 and CA 125 have been studied for their potential to differentiate between malignant and non-malignant ascites." (PMID 41010973, 2025). "In December 2014, a follow-up ultrasound revealed enlarged lymph nodes in zones IV and V of the left neck, and AFP was elevated to 54.1 ng/ml, suggesting local tumor recurrence." (PMID 41561743, 2025). "MiR-21 was strongly negatively correlated with CA 19-9 (r = −0.709) and CEA (r = −0.587), and positively with AFP (r = 0.647), suggesting inverse relationships with certain tumor markers but a direct relationship with AFP." (PMID 41464526, 2025). "High expression of LINC01348 was associated with better overall survival of patients with HCC and negatively correlated with pathological stage, grade of tumor and AFP serum levels." (PMID 40596757, 2025). "This regimen was effective against his tumor, which was 18 × 14 × 66 mm before the operation, with AFP level decreasing to within the normal range." (PMID 41000245, 2025).
tumor (continued). "The results of this study showed that the survival advantage of TACE therapy was particularly prominent in patients with high AFP level or tumor diameter≥ 5 cm compared with radical hepatectomy alone." (PMID 41200181, 2025). "Despite multimodal treatment approaches, the patient experienced progressive disease with increasing tumor burden and AFP levels." (PMID 40922714, 2025). "Elevated DAP3 levels were correlated with increased AFP levels (P=0.044) and larger tumor size (P=0.024)." (PMID 40051634, 2025). "Tumor characteristics were similar between groups, including alpha-fetoprotein level, maximum tumor size, and locoregional treatments." (PMID 40078822, 2025). "In the multivariate analysis, tumor burden, AFP, therapeutic modality, and radiologic pattern were independent predictors of PFS." (PMID 41199230, 2025). "While AFP reflects tumor burden and immune evasion, CRP serves as a proxy for systemic inflammation—two critical biological dimensions that impact immunotherapy responsiveness." (PMID 41358154, 2025). "Laboratory results indicated elevated tumor markers: AFP > 2000 ng/mL, CEA 2.19 ng/mL, cytokeratin 17.21 ng/mL, and CA19‐9 14.43 μ/mL." (PMID 40035422, 2025). "Large tumor size (>5.9 cm), high alpha-fetoprotein (AFP > 40–400 ng/mL), and major vascular invasion were independently associated with PVT in multiple studies." (PMID 41228207, 2025). "Postoperatively, FIF must be screened with frequent follow-up visits and tumor markers, i.e., alpha-fetoprotein." (PMID 40297260, 2025). "IL-12 was positively correlated with ECOG (r = 0.190, p<0.05), AFP (r = 0.247, p<0.05) and intrahepatic tumor size (r = 0.230, p<0.05), and IL-6 was positively correlated with intrahepatic tumor size (r = 0.217, p<0.05)." (PMID 40568585, 2025). "Given the unresectable and HER2‐negative nature of the cancer, chemotherapy with TS‐1 and cisplatin was initiated, resulting in a temporary reduction in AFP levels and tumor size." (PMID 40922714, 2025). "Conversely, INR correlations with other tumour markers, including CA 19-9, CA 125, and AFP, remained weak across all histopathological groups." (PMID 40332145, 2025). "Before exception approval, evidence of treatment response (mRECIST), stabilised tumour markers (for example, decreasing AFP), and restaging with CT or MRI are required, with PET or radiomics used to detect covert MVI." (PMID 41301037, 2025). "Tumor-related factors such as poor differentiation, vascular invasion, and elevated tumor biomarkers like alpha-fetoprotein are key predictors of recurrence." (PMID 40427147, 2025). "In the case of our patient, venous expansion, thrombus enhancement, and elevated AFP levels were present, which are suggestive of a tumor thrombus." (PMID 39717215, 2025). "This is worth noting, as AFP is a commonly used tumor marker for assessing tumor burden and prognosis of HCC." (PMID 41267711, 2025). "At one month, follow-up CT at matched anatomic levels showed interval tumor shrinkage with decreased arterial-phase hyperenhancement, and AFP and PIVKA-II had fallen to within the institutional reference ranges." (PMID 41450371, 2025). "Clinical characteristic analyses showed that elevated risk scores were significantly associated with adverse clinicopathological features, including AFP >= 400 ng/ml, age<60 years, poor pathological grade, larger tumor size and advanced TNM stage." (PMID 41048998, 2025). "Significant differences between the two groups were observed in age, HBV, WBC, AFP, Child-Pugh classification, tumor size, PVTT, M status, and BCLC stage." (PMID 41458972, 2025).
tumor (continued). "Tumor markers (beta human chorionic gonadotropin, alpha fetoprotein, and alkaline phosphatase isoenzymes in both cerebral spinal fluid and serum) were within normal range." (PMID 40136376, 2025). "○ To date, this study explores various biomarkers, including alpha-fetoprotein, circulating tumour DNA (ctDNA), microRNAs, and proteins, evaluating their diagnostic performance and suitability for use in low-resource environments." (PMID 40343687, 2025). "Classical pediatric tumor markers (AFP, β-hCG, HVA/VMA, LDH, ALP) largely reflect late biological consequences and often remain within normal ranges during early stages of childhood cancers." (PMID 41514520, 2025). "Serum tumor markers: Alpha-fetoprotein (AFP), beta-human chorionic gonadotropin (beta-hCG), and lactate dehydrogenase (LDH) were all within normal limits." (PMID 39974304, 2025). "A presumptive diagnosis of PMNSGCT can be made based on CT scan findings and elevated serum tumor markers (alpha-fetoprotein (AFP), beta human chorionic gonadotropin (HCG), and lactate dehydrogenase (LDH)) in most cases, as was for our patient." (PMID 40443838, 2025). "Baseline data, intestinal barrier function (DAO, D-lac, LPS), tumor markers (AFP, CA19-9, CA-125, CEA), MHBT positivity rate and relative abundance of intestinal flora were analyzed in the two groups, and diagnostic efficacy was assessed by ROC curve." (PMID 40520790, 2025). "Patients with HCC who maintain a normal range of AFP levels and the disappearance of blood flow in the tumor on CT or MRI are generally considered to be in a necrotic state." (PMID 40055288, 2025). "Tumor markers alpha-fetoprotein (AFP), carcinoembryonic antigen (CEA), cancer antigen 125 (Ca-125), and carbohydrate antigen 19–9 (CA19-9) were within normal range." (PMID 40671141, 2025). "To assess the effect on tumor cell growth, we quantified, in the culture media, the levels of the liver tumor biomarker alpha-fetoprotein (AFP)." (PMID 41465318, 2025). "Circular RNAs 0009910 and 0027478 exhibit significant positive correlations with tumor size and AFP levels (p < 0.001)." (PMID 40429981, 2025). "When considered alongside traditional serum tumor markers (AFP, β-hCG, and LDH), these inflammatory markers contribute to a more comprehensive characterization of tumor burden and biological aggressiveness." (PMID 41283275, 2025). "Tumor markers included alpha-fetoprotein (AFP) at 50,380 ng/ml (reference range: 0.0–2,000 ng/ml), carcinoembryonic antigen (CEA) at 1.5 ng/ml (reference range: 8.1–62 ng/ml), and neuron-specific enolase (NSE) at 29.6 ng/ml (reference range: 21–39.2 ng/ml)." (PMID 40980129, 2025). "The combined diagnostic model, integrating blood routine parameters (e.g., WBC, NLR, LMR) and tumor markers (e.g., AFP, CA19-9), demonstrates high clinical operability due to its reliance on routinely available and cost-effective tests." (PMID 40128070, 2025). "In clinical practice, the diagnosis and monitoring of PLC heavily rely on specific tumor markers, among which Alpha-fetoprotein (AFP) is the most widely used." (PMID 41211432, 2025). "Multivariate Cox regression analysis identified tumor size >5 cm, AFP > 200 μg/L, GGT >104 μ/L, and MPV <10.2 fL as independent indicators of poor prognosis in HCC patients." (PMID 40091304, 2025). "In multivariate analysis, tumor size decline ratio (OR=0.002; 95% CI: 0.000–0.117; p=0.002) and AFP decline ratio (OR=0.240; 95% CI: 0.067–0.862; p=0.029) during conversion therapy independently predicted a lower recurrence risk." (PMID 40934000, 2025). "High DUSP9 expression was positively correlated with elevated serum AFP levels, large tumour size and poorer differentiation in our HCC tissue microarray cohort." (PMID 41383134, 2025). "It is well known, however, that parameters such as tumor burden, plasma AFP levels, the presence of microvascular invasion, and tumor differentiation significantly impact survival rates following liver transplantation." (PMID 40709064, 2025).